PCNA (proliferating cell nuclear antigen)
Diseases named in the same sentence as PCNA in open-access papers (continued):
Sharing a sentence is not in itself a finding about the gene and the disease.
tumor (continued). "PCNA was mainly located in the nucleus of tumor epithelial cells and little was expressed in non-tumor salivary gland tissues." (PMID 23599795, 2013). "Proliferating cell nuclear antigen (PCNA) is a protein that is widely expressed in the S phase of the cell cycle, and the levels of PCNA reflect the proliferative activity of the tumor cells." (PMID 24137341, 2013). "Oral administration of the inhibitor resulted in a significant decrease in brain tumor burden, reduced CD31-positive vessels in the brain lesions and incidence of PCNA positive tumor cells, and increased apoptosis in the tumor." (PMID 23340652, 2013). "Noteworthy, both proteins were over-expressed in 95% of the tumor samples analyzed, which also showed significant PCNA staining which evidenced their active proliferative status." (PMID 23301044, 2013). "Immunohistochemistry analysis was subsequently performed to examine Ki67 (an anti–proliferating cell nuclear antigen) expression in HCC tumor tissues." (PMID 24391821, 2013). "Quantitative relationships between PET, thymidine kinase 1 (TK1) protein levels and immunostaining for proliferation markers (Ki67, TK1, PCNA) were evaluated using imaging-matched tumor specimens." (PMID 23554961, 2013). "Using immunohistochemistry, we observed low PCNA protein expression in tumor cells after heated lipiodol perfusion." (PMID 23637861, 2013). "Combination treatment with oxaliplatin and Exendin4 can significantly decrease Ki67 and PCNA proteins expression in subcutaneous tumor of nude mice." (PMID 24351817, 2013). "Many investigations of tumor-cell proliferative activity have used PCNA and Ki-67 to evaluate cell proliferation in oral tumors." (PMID 23229269, 2013). "Immunohistochemistry analyses to determine mitotic (PCNA-labelled) and apoptotic cell counts were performed in unstained sections of the tumor xenografts." (PMID 24040114, 2013). "According to such tissue organization, histochemistry revealed a prevalence of cell proliferation at the tumor surface (according to PCNA staining), whereas the internal portion was characterized by a prevalence of apoptosis (according to TUNEL assay)." (PMID 23526965, 2013). "Levels of PCNA are considered to be a reliable indicator of cell proliferation, due to the correlation between PCNA levels and the proliferative activity of tumor cells." (PMID 24137341, 2013). "Using expression array data in combination with immunohistochemical staining, in the present study we found that tumor samples with high PCNA+ TAMs demonstrated higher expression of several M1-related genes, but not M2-type genes." (PMID 24205370, 2013). "Double staining showed that EpCAM and PCNA were co-expressed in numerous tumor cells, particularly in dysplastic ductal tumor cells." (PMID 23251255, 2013). "Overall, the tumor volume and the PCNA LI% within live tumor areas were reduced by 83% and 99%, respectively, in all TAM-treated groups when compared to the untreated control group." (PMID 23634930, 2013). "In this report, we have identified novel interaction between HLA I and PCNA on the surface of human tumor cells by confocal microscopy and immunoprecipitation." (PMID 23527218, 2013). "The percentage of positive staining cells (PCNA proliferation index) and the intensity of staining, varied from one area to another in each tumor." (PMID 24198832, 2013). "ZEB1 positive tumours showed a significant enrichment for PCNA and EGFR, while NF1 deletions were significantly more prevalent in ZEB1 negative specimens." (PMID 23818228, 2013). "Proliferating cell nuclear antigen (PCNA) expression in the tumor was assessed through immunohistochemical staining." (PMID 23637861, 2013). "This suggests that the combination therapy resulted in inhibition of tumor progression which is also reflected by the reduced expression of the proliferation markers PCNA in these tissues." (PMID 23342262, 2012).
tumor (continued). "Ki-67 is considered to be a more accurate marker of the proliferative stage of tumour cells than proliferating-cell nuclear antigens (PCNA), and Ki-67 immunoreactivity has been reported to correlate with the prognosis of many cancers." (PMID 22452794, 2012). "Cyclin D1, a member of G1 cyclins, and PCNA (proliferating cell nuclear antigen) are commonly used to assess tumor cell proliferation." (PMID 22879971, 2012). "Cell proliferation marker PCNA and cell apoptosis were further examined in situ in tumor samples from the four groups." (PMID 22666346, 2012). "PDTC treatment inhibited the expression of the key cell cycle regulators cyclin D1, cyclin E1, and PCNA in both tumors and in non-tumor bearing epidermis." (PMID 22761871, 2012). "Immunoblot analysis of tumor lysates of mice also revealed downregulation of Bcl-2, Bcl-XL, cIAP1, and Survivin as well as PCNA in lung tumors after PG treatment." (PMID 23284890, 2012). "Tumor xenografts from A. blazei-fed mice showed decreased proliferating cell nuclear antigen-positive cells and reduced tumor microvessel density." (PMID 22582152, 2012). "We first performed PCNA staining to assess the effect of combination-therapy groups, suppression on tumor cell proliferation." (PMID 22529899, 2012). "After pretreatment with anti-c-Kit, the number of PCNA-positive tumor cells was significantly higher compared to controls (P < 0.05)." (PMID 21977032, 2012). "PCNA as an indicator of cell proliferation displayed positive staining in 46.9 ± 3.1% of the tumor cells in control animals." (PMID 21977032, 2012). "The immunohistochemical analysis of tumor sections, stained with H&E and for proliferation antigen PCNA, revealed greater inhibition of tumor cell growth in CCR5−/− mice." (PMID 22567084, 2012). "PCNA is markedly expressed in proliferating cells and in most malignant tumor cells, and is therefore used as a proliferative/malignancy biomarker in cancer." (PMID 22574207, 2012). "The expression of GPER and PCNA staining appear to localize to the same regions suggesting that GPER is overexpressed in proliferating tumor cells." (PMID 23273253, 2012). "The proliferation of HepG2 within the tumor mass detected by PCNA, was significantly reduced in MV-HLSC treated tumors with respect to control mice injected with vehicle alone, with MV-RNase or with MV-CD29." (PMID 22736596, 2012). "In contrast, additional blockade of SDF-1 resulted in a significantly lower number of PCNA-positive tumor cells compared to controls and to anti-c-Kit pretreated animals (P < 0.05)." (PMID 21977032, 2012). "Further analysis of tumors harvested at the end of the study revealed a significant reduction in tumor cell proliferation as measured by PCNA staining and an increase in cleaved caspase-3 levels, a marker of apoptosis." (PMID 22295124, 2012). "The IHC analysis of DU145 tumor samples showed that flavonolignans treatment significantly inhibits the immunostaining for PCNA (a biomarker for cell proliferation), but increases the TUNEL and cleaved-caspase 3 positive cells (biomarkers for apoptosis)." (PMID 22514647, 2012). "The MCF-7 cell/CAF and MDA-MB-231/CAF mixed nodules showed a significantly larger proportion of Ki67- or PCNA-positive tumor cells with respect to that observed in the homotypic cultures as well as in the mixed nodule sections of tumor cells and NFs." (PMID 23251387, 2012). "Numerous experimental data have, shown a positive correlation of MT expression and Ki-67 or PCNA (proliferating cell nuclear antigen) antigens in human tumour tissues, supporting the pro-proliferative role of MTs." (PMID 23273222, 2012). "As HSCs promoted Hepa1–6 proliferation in vitro, the in vivo pro-proliferative response of HSCs was then assessed by analysing tumour samples using PCNA immunostaining." (PMID 22641338, 2012).
tumor (continued). "In order to further clarify this issue, immunohistochemisty of CD31 and PCNA were carried out to investigate the microvessel density and tumor proliferation of MMQ cell xenografts in both rhEPO and control groups." (PMID 22086127, 2012). "This was accompanied by increased levels of proliferating cell nuclear antigen (PCNA) staining within the tumor implying higher proliferation in the arthritic versus the non-arthritic tumors." (PMID 21859454, 2011). "Immunohistochemistry was performed on the tumours to evaluate the effects of the drugs on phosphorylated and total c-Myc levels and tumour proliferation (PCNA)." (PMID 22015557, 2011). "The immunoreactivity of PCNA was found less frequently in the nuclei of SNU-668IκBαM tumour cells than in those of SNU-668Vector tumour cells (P=0.012)." (PMID 21119667, 2011). "This puts PCNA in a central position in determining the fate of replication fork, which ultimately determines both tumor progression as well as the outcome of anticancer treatment." (PMID 21247416, 2011). "We stained tumour sections with an antibody directed against proliferating cell nuclear antigen (PCNA) and counted PCNA-positive cells to determine the proliferative capacity of the tumour." (PMID 21609428, 2011). "In contrast, CDK2 and PCNA appeared to be up-regulated in all HCC tissues compared to non-tumor tissues." (PMID 22132221, 2011). "The density of PCNA, a proliferation marker of tumor cells, was evidently higher in tumor tissues from BGC/STC mice and lower in tumor tissues from BGC/shSTC mice than that from BGC mice, BGC/CON mice or BGC/shCON mice." (PMID 21672207, 2011). "In others terms, these results suggest that the DNA is less methylated in tumor cells than in non-tumor cells since tumors cells harbored less Dnmt1/PCNA interactions." (PMID 21470401, 2011). "PCNA is now one of the most commonly used molecules to detect the proliferation index of tumor cells." (PMID 20092659, 2010). "Further staining with Ki-67, PCNA and mTrop2 confirmed the presence of mTrop2 expressing tumor cells inside the liver which also showed increased Ki-67 and PCNA expression." (PMID 20858281, 2010). "Epithelial cell proliferation in normal and cancerous lungs can be measured efficiently by quantifying the percentage of tumor cells positive for PCNA." (PMID 21203518, 2010). "To corroborate these findings of specific MPE, but not tumor growth suppression by NF-κB-tailored bortezomib treatment, we next assessed the proliferation and apoptosis of tumor cells in vivo using PCNA and TUNEL labeling, respectively." (PMID 20219102, 2010). "At the same time, expression of VEGF and PCNA was markedly decreased in tumor tissues in the control group." (PMID 20667141, 2010). "Tumor cell proliferation was measured by counting Ki67 and PCNA positive cells, and apoptosis was measured by counting TUNEL positive cells." (PMID 21209944, 2010). "Cyclin D1 and PCNA were expressed by terminal duct epithelial cells, gland alveolus cells and tumor cells." (PMID 20092659, 2010). "To examine the effect of TGZ on tumor growth, we performed immunohistochemistry for PCNA, which is expressed in the nuclei of proliferating cells, using the primary tumor sections." (PMID 20170548, 2010). "Compared with groups II and III, the percentage of positive MMP-9, VEGF and PCNA tumor cells in group I was even higher (P < 0.05)." (PMID 20667141, 2010). "Cases were reviewed and analyzed for the immunohistochemical expression of PCNA, Ki67, p27, p16, p57, p21, cyclin-D1 and c-myc and correlated to clinico-biological endpoints of tumor size, node status, stage of the disease, and disease free survival (DFS)." (PMID 20152033, 2010). "Because CPT-TMC inhibited cell proliferation obviously in vitro, we first examined its effects on tumor cell proliferation by PCNA staining to explore the potential mechanisms of CPT-TMC therapy in vivo." (PMID 20565783, 2010).
tumor (continued). "For the purpose, we analyzed the effect of LETM1 on tumor cell proliferation using proliferating cell nuclear antigen (PCNA) antibody." (PMID 20824095, 2010). "Resveratrol and TRAIL alone inhibited growth of PC-3 xenografts in nude mice by inhibiting tumor cell proliferation (PCNA and Ki67 staining) and inducing apoptosis (TUNEL staining)." (PMID 21209944, 2010). "Staining for synaptophysin, a marker of primitive neurons was weak in both tumor types, but appeared to overlap with staining for PCNA." (PMID 20520772, 2010). "The percentage of positive MMP-9, VEGF and PCNA tumor cells in the RFA treatment groups were markedly higher than that in the control group (P < 0.05)." (PMID 20667141, 2010). "Cell division is further indicated by PCNA immunostaining of invasive tumour cells in the zebrafish embryo." (PMID 19400945, 2009). "Consistent with the observed decrease in tumor growth, the proliferation ratio of LNCaP and C4-2 tumors was also decreased, as quantified by PCNA staining in tumors electroporated with miR-143." (PMID 19855844, 2009). "Immunohistochemistry revealed diffuse nuclear accumulation of PCNA and Ki67 in the tumor cells of branch dusts." (PMID 19841679, 2009). "The impact of PEG-LPrA2 treatment on proliferation markers (PCNA and cyclin D1) was further investigated in tumor lysates by western blot analysis." (PMID 19531256, 2009). "We investigated cell proliferation, cell cycle distribution, pRb phosphorylation, and mRNA expression of E2F-1 and PCNA in tumor cells after treatment with CKIA and CKIB." (PMID 19551155, 2009). "Decreased tumour growth was due to reduced proliferation and increased apoptosis (as assessed by PCNA and caspase-3 immunostaining)." (PMID 19240717, 2009). "The number of tumor cells positive for PCNA staining in the treatment group was less than observed in the control group." (PMID 18983651, 2008). "Results of PCNA immunohistochemical staining indicated that the tumor cells in the treatment group had a lower proliferative ability than that in the control group." (PMID 18983651, 2008). "Those experiments indicate that the level of PCNA expression increases as tumor malignancy increases." (PMID 18366613, 2008). "Because tumors proliferate faster than normal cells, expression level of PCNA can sensitively reflect the degree of tumor cell proliferation." (PMID 18366613, 2008). "Within 24 h the tumor cell fraction was reduced 1.9-fold while the stromal cell fraction increased >3-fold, consistent with specific reductions in phospho-pp44/42 MAPK, MEK1/2 and PCNA in tumor cells and reciprocal increases in the stromal cells." (PMID 18435859, 2008). "Tumor tissues derived from curcumin treated mice showed that curcumin inhibibited proliferation (PCNA and Ki67 staining), induced apoptosis (TUNEL staining), metastasis (uPA, MMP-2 and MMP-9 staining), and angiogenesis (CD31 and VEGF staining)." (PMID 18226269, 2008). "In benign diseases only 3.8% cells were positive to PCNA, while in tumor cases this percentage increased to 19% (in situ) and to 23.8% (infiltrating)." (PMID 17697357, 2007).
tumor (continued). "No noticeable difference was observed between drug-sensitive germline tumour cells and a drug-resistant cell (Hey) in the expression of DNA repair proteins (PCNA, TFIIH, DNA-PKcs, and Ku70/80)." (PMID 15655552, 2005). "Consistent with the cell proliferation and animal tumour growth data observed, cyclin D1 and PCNA index were significantly decreased by NS-398 both in vitro and in vivo." (PMID 14760389, 2004). "To further assess the inhibitory effects of NS-398 on cell proliferation and tumour growth, we measured cyclin D1 and PCNA levels using Western blot hybridisation and immunohistochemistry." (PMID 14760389, 2004). "Mice treated with ZD6126 demonstrated a 59% decrease in PCNA-positive cells (P< 0.02), indicating reduced tumour cell proliferation." (PMID 14760388, 2004). "Overexpression of ephrin-B2 led to an increase in tumour angiogenesis (vessel count by CD31 staining) but a decrease in tumour size and tumour cell proliferation (PCNA staining)." (PMID 15083195, 2004). "In the present study, the PCNA index was significantly increased in gastrin-treated tumours when compared with control." (PMID 12189559, 2002). "The synthesis and expression of PCNA are enhanced in proliferating cells including those that are tumour-derived." (PMID 12189559, 2002). "Consistent with tumour growth, cyclin D1 protein and PCNA index in tumour tissues were significantly greater in the tumour tissue of G-17 treated mice." (PMID 12189559, 2002). "Analisar 11 casos de carcinoma mucoepidermóide (CME) através do antígeno nuclear de proliferação celular (PCNA) e determinar sua relação com o grau de malignidade destes tumores." (PMID 10810331, 2000). "Contrary to the results obtained by Tsai & Jin,27 the data of the present study showed a statistically significant difference between the malignancy grades and the expression of PCNA in tumor cells, as evaluated by the percentage of positive cells." (PMID 10810331, 2000). "Immature tumour cells adjacent to thin fibrovascular stroma are proliferating, as evidenced by PCNA positivity, and often express Bcl-2." (PMID 9099968, 1997). "An increase of the spot density of the PCNA polypeptide was observed in rapidly proliferating tumour cells, confirming the validity of the procedures used." (PMID 8932346, 1996). "The results showed that prognosis was significantly worse in patients who had a tumour with a high MVC (16 or greater) or a high PCNA LI (42% or greater) than in those patients who had a tumour with a low MVC (less than 16) or a low PCNA LI (less than 42%)." (PMID 7543771, 1995). "Microvessel count (MVC; the mean number of microvessels in the five areas of highest vascular density at 200 x magnification) and PCNA labelling index (PCNA LI; percentage of positive cells in more than 500 tumour cells) were determined." (PMID 7543771, 1995). "PCNA induction the normal cells surrounding tumours is a direct example of the effect of tumour cells on normal surrounding tissues." (PMID 7914422, 1994). "In survival analysis the fraction of PCNA/cyclin positive nuclei predicted survival in the entire cohort (P less than 0.001) and in Ta-T1 tumours (P = 0.0005)." (PMID 1353364, 1992). "Tumor presence was associated with increased expression of LH and FSH receptors and c-KIT, while angiogenic and proliferative factors (PCNA, Ki-67, IGF-1, VEGF, and ERα) showed lower expression." (PMID 42121783, 2026). "DBT + PTX synergistically reduced tumor volume and proliferation markers (Ki67/PCNA)." (PMID 42075862, 2026). "Additionally, proliferating cell nuclear antigen (PCNA) fluorescence staining indicated a decrease in PCNA‐positive cells at the tumor site treated with a combination of IDET and taxol." (PMID 41394539, 2025).